Y_RNA (Y RNA )
Gene: Miscellaneous RNA gene on chromosome 6 (38,565,950 to 38,566,055, forward strand). Ensembl gene ENSG00000199938.
Homologues: Orthologues: chimpanzee Y_RNA (99% identical), macaque Y_RNA (99% identical). Paralogues in human: RNY1P13 (90% identical), RNY1 (88% identical), Y_RNA (88% identical), Y_RNA (87% identical), Y_RNA (86% identical), RNY1P11 (85% identical), Y_RNA (85% identical), Y_RNA (84% identical), Y_RNA (83% identical), RNY1P8 (82% identical), Y_RNA (82% identical), RNY1P7 (81% identical), and 99 more.